CNTNAP3B (contactin associated protein family member 3B)
Tractability: Antibody: UniProt predicts a signal peptide or a membrane-spanning region.
Gene: Protein-coding gene on chromosome 9 (41,890,314 to 42,129,552, reverse strand). Ensembl gene ENSG00000154529.
Subcellular location: Membrane
Gene Ontology:
Biological process: nervous system development; signal transduction
Cellular component: plasma membrane; synapse; membrane
Genetic constraint (gnomAD): Loss-of-function variants: 17 observed, 36.43 expected, observed/expected ratio (o/e) 0.47, 90% interval 0.32 to 0.7. The synonymous counts are far from expectation, so gnomAD's model fits this gene poorly and the ratio says little. Missense variants: 190 observed, 419.29 expected, observed/expected ratio (o/e) 0.45, 90% interval 0.4 to 0.51. Synonymous variants: 86 observed, 142.1 expected, observed/expected ratio (o/e) 0.61, 90% interval 0.51 to 0.72.
Homologues: Orthologues: chimpanzee CNTNAP3 (81% identical), rat Cntnap3 (74% identical), mouse Cntnap3 (74% identical), tropical clawed frog cntnap4 (58% identical), zebrafish cntnap3 (51% identical). Paralogues in human: CNTNAP3 (98% identical), CNTNAP4 (70% identical), CNTNAP5 (53% identical), CNTNAP2 (46% identical), CNTNAP3C (38% identical), CNTNAP1 (36% identical), NRXN2 (24% identical), NRXN3 (23% identical), NRXN1 (22% identical), CUBN (17% identical), HEPH (14% identical), HEPHL1 (14% identical), and 23 more.
Diseases named in the same sentence as CNTNAP3B in open-access papers:
CNTNAP3B is named in the same sentence as 4 diseases in open-access papers, as found by Europe PMC text mining. Sharing a sentence is not in itself a finding about the gene and the disease. The quoted sentences say what the papers report.
psoriasis (1 paper, 2016). An autoimmune condition characterized by red, well-delineated plaques with silvery scales that are usually on the extensor surfaces and scalp. "Most of the upregulated transcripts (PNvsC) were induced also in the lesions (PLvsC), except CNTNAP3B and the mitochondrial transcripts (ChrM) named in the alignment step as TVAS5, both of which have not been implicated in psoriasis before." (PMID 26976200, 2016).
viral infection (1 paper, 2021). "CNTNAP3B, like CNTNAP3, is a cell-recognition molecule mediating glial cell contacts and has not been identified as part of the host response to viral infection." (PMID 34777354, 2021).
cancer (1 paper, 2017). A tumor composed of atypical neoplastic, often pleomorphic cells that invade other tissues. "Those CNC variations associated with poor outcome (MUC5B, ZXDB, PLIN4, CCDC144NL, CNTNAP3B, and CCDC180) may probably facilitate cancer initiation and progression, and may be a new clue to study cancer metastasis and evolution." (PMID 29262625, 2017).
CNTNAP3B also shares sentences with these, for which no sentence is quoted: alcoholic fatty liver disease (1 paper).